CDK2 (cyclin dependent kinase 2)
Diseases named in the same sentence as CDK2 in open-access papers (continued):
Sharing a sentence is not in itself a finding about the gene and the disease.
cancer (continued). "Transfection of antisense oligonucleotide of miR-25 has downregulated the overexpressed miR-25 in SCLC cell line, resulting in decreased amount of cancer cell proliferation, invasion, and resistance to cisplatin by suppressing the expression of CyclinE2 and CDK2." (PMID 36303933, 2022). "Importantly, our preclinical findings also illustrate how pharmacologic manipulation of key cell cycle regulators (CDK1 and/or CDK2) can potentially limit the efficacy of WEE1 inhibitors in cancer patients." (PMID 35315355, 2022). "Interestingly, Cdk2 has been reported to be a client of Hsp90, and Hsp90 inhibitor treatment significantly reduces levels of Cdk2 in cancer cells." (PMID 35039060, 2022). "63% ( ± 21%) of cancer cells expressed the CDK2/4 inhibitor p16INK4a." (PMID 35844581, 2022). "In addition, CDK2 overexpression significantly attenuated the anti-cancer effect of erdafitinib by affecting the transcriptional activity and expression of E2F1, as well as the expression of CDK1." (PMID 36235266, 2022). "Cyclin-dependent kinase 2 (CDK2) complex is significantly over-activated in many cancers." (PMID 35595767, 2022). "Our data indicated that erdafitinib regulated E2F1-CDK1 signaling by affecting CDK2 expression; however, whether the drug enters the cancer cell to exert its effect needs to be further studied." (PMID 36235266, 2022). "CDK1, CCNB1 and CDK2 are the key oncogenes that promote cell cycle progression in cancer cells." (PMID 35359459, 2022). "Moreover, Comp1 and Comp2 significantly blocked the interaction between CCNA2 and CDK2, leading to irreversible arrest of the cell cycle of cancer cells." (PMID 36325324, 2022). "In this context, the degradation mechanism we have identified may open a potential avenue towards CDK2-targeted cancer therapies." (PMID 35595767, 2022). "In addition, in this type of cancer, combined inhibition of CDK2 and CDK4/6 has enhaced sensitivity to palbociclib." (PMID 36266723, 2022). "Up-regulation of CDK2 has been reported in diverse types of cancers." (PMID 36266723, 2022). "Our results identify an autophagic degradation mechanism of the CDK2 protein in cancer cells." (PMID 35595767, 2022). "It has been shown that STC1 played a crucial role in promoting tumor metastasis, invasion, tumor cell proliferation, and antiapoptosis via participating in multiple signal pathways associated with cancer, including JNK/c-Jun NF-κB, cyclin E/CDK-2, and ERK1/2 signal pathways." (PMID 35273656, 2022). "Moreover, this binding both inhibited the activity of CDK2 and induced its degradation in cancer cells." (PMID 35595767, 2022). "On the contrary, CDKN3 was reported as a tumor suppressor in some cancers as it is a negative regulator of Cyclin-dependent kinases (CDK1 and CDK2) but the exact effect of CDKN3 in cancer cell proliferation, either enhancing or precluding, it cannot be explained by its CDK regulation, alone." (PMID 35446856, 2022). "EGFR initiates a signaling cascade that leads to DNA synthesis and cell proliferation; and EGFR and PI3K initiate malignant transformation of cancer cells by activating other pathways such as Myc and Rb-E2F, which in turn leads to the formation of cyclinD/Cdk4 and cyclinE/Cdk2 complexes." (PMID 34658851, 2021). "Among, 10953 patients/10967 samples of all type of human cancers publicly available in the online cancer genomic database cBioPortal, genetic alterations of CDK2/4/6 and STAT3 occurs in 825 (8%) patients, comprising 127 (1.2%) CDK2, 307 (2.8%) CDK4, 266 (2.4%) CDK6, and 220 (2%) STAT3 and." (PMID 33668805, 2021). "Therefore, dire needs to develop small molecule inhibitors that target CDK2 with potential and specificity to overcome resistance among cancer cell populations." (PMID 33466812, 2021). "The expression, stage and prognosis of CDK2 were obviously different in many cancers." (PMID 34409029, 2021).
cancer (continued). "Accumulating evidence suggests that overexpression of CDK2 may lead to abnormal cell cycle regulation, which may be directly related to overproliferation of cancer cells 45-48." (PMID 33746605, 2021). "For different types of cancer, we conducted paired differential expression of CDK2." (PMID 34409029, 2021). "Together, these data indicate that oncogenic activation of Cyclin E/CDK2 complex drives numerous forms of genomic instability in human cancers, ranging from whole chromosomal gains and/or losses to focal genomic deletions and/or amplifications, as well as chromosome rearrangements." (PMID 34901021, 2021). "Using the R package, we ranked CDK2 by its expression in 33 cancers." (PMID 34409029, 2021). "Aberrant CDK2/4/6 expression may enhance cancer progression, in part, through influence on mechanisms that maintain cell cycle progression." (PMID 33668805, 2021). "Similarity, using pull-down assays, they also found that circFOXO3 regulates the cell cycle in the form of the circFOXO3-p21-CDK2 ternary complex in mouse non-cancer cells, which can enhance the interplay of CDK2 with p21 and inhibit the phosphorylation of CDK2." (PMID 34745938, 2021). "Indeed, we found that genetic alterations in CDK2/4/6 co-occurred with a number of other genetic alterations in the cancer cohorts." (PMID 33668805, 2021). "In the present study, we identified the frequencies of genetic alterations of STAT3/CDK2/4/6 in multiple cancer types, identified the gene signature as oncogenic prognosticators of CAFs and tumor immune infiltration, and poor prognoses of clinical cancer cohorts." (PMID 33668805, 2021). "The synthesized compounds were screened for their cytotoxicity to investigate their anti-cancer activity against; four human A-2780 (ovarian), HT-29 (colon), MCF-7 (breast), and HepG2 (liver) cancer cell lines and subsequent testing of CDK2 inhibition activity of the most active derivatives." (PMID 34769385, 2021). "We analyzed the prognostic relevance of CDK2, CDK4, and CDK6 genetic alterations and found that CDK4 and CDK6 alterations are associated with low overall survival, disease-free survival, and progression-free survival of cancer cohorts (p < 0.05)." (PMID 33668805, 2021). "In order to verify CDK2 in all kinds of cancers, we carried out a pan-cancer study." (PMID 34409029, 2021). "Moreover, a simultaneous use of MM-129 with 5-FU enhances the sensitivity of cancer cells through Akt, mTOR, and CDK2 inhibition." (PMID 34206937, 2021). "Since cyclin E1/CDK2 protects cells from DNA damage and cyclin E1 is elevated in BRCA1 mutant cancers, we hypothesized that CDK2 inhibition would sensitize these cancers to PARP inhibition." (PMID 34465787, 2021). "Mechanistic studies demonstrate that esomeprazole arrests cancer cells in the G1 phase of the cell cycle through upregulation of p21 protein and inhibition of cyclin-dependent kinases (Cdks) type 1 (Cdk1) and type 2 (Cdk2)." (PMID 34262645, 2021). "Cyclin dependent kinases (CDKs), such as Cyclin D/E and CDK2/4/6, which are involved in promoting cell cycle progression, are often overexpressed, while cyclin-dependent kinases (CDKIs), such as p21 and p27, are generally downregulated in cancer cells." (PMID 34195076, 2021). "Furthermore, high levels of Cyclin E and/or increased activity of CDK2 have been observed in numerous cancers, ranging from hematological malignancies to numerous solid tumors, and are associated with poor prognosis and decreased survival in cancer patients." (PMID 34901021, 2021). "As previously reported, CCNE2, which is frequently observed in proliferation, or migration in various kinds of cancers, is one of the two regulatory subunits of cyclin-dependent kinase 2 and could regulate the progression from G1 to S phase in cells." (PMID 34568326, 2021).
cancer (continued). "In mouse cancer cells, circ-Foxo3 suppresses cell cycle progression by interacting with cyclin-dependent kinase 2 (CDK2) and cyclin-dependent kinase inhibitor 1 (p21) to form a circFoxo3-p21-CDK2 ternary complex, thereby arresting the functions of p21 and CDK2 in cell cycle regulation." (PMID 33717154, 2021). "Therefore, CDK2 is a promising target for neurodegenerative disorders, cerebral hypoxia, and cancers." (PMID 32575562, 2020). "CDK2 is a potential therapeutic target in many cancers including HCC." (PMID 32807134, 2020). "Finally, we review the literature of pertinent CDK2 inhibitors from the preclinical to clinical stages, mostly developed to treat various cancers." (PMID 32543655, 2020). "MiR-5582-5p by targeting GAB1, SHC1, and CDK2 could induce apoptosis and cell cycle arrest at G1 phase in cancer cells." (PMID 33330110, 2020). "The molecules were screened against ABL, CDK2 and two cancer cell lines." (PMID 33479617, 2020). "Thus the predominant pharmacological effect of fadraciclib on cancer cells is likely to be mediated by inhibition of CDK2 and CDK9." (PMID 32645016, 2020). "CAPE and CAPE-pNO2, by reducing the concentration of CDK2, might induce pRb dephosphorylation to promote cancer aging and stop the cell transition from the G1 to S phase." (PMID 32752091, 2020). "And 23 of the 25 functional genes were significantly up-regulated in COAD, such as CDK1, CDK2, CDK4, CDK6, and CDK7, which can cause uncontrolled proliferation and may serve as promising targets in cancer therapy." (PMID 32680494, 2020). "The study of CDK2 inhibitors also provided new prospects for cancer treatment." (PMID 32699532, 2020). "There are many evidences supporting the idea of targeting CDK2 to control cancer progression." (PMID 31847444, 2019). "Many studies have suggested that CDK2 could be a crucial factor in the progression of cancer by regulating several pathways and might be a prospective biomarker and indicator of prognosis." (PMID 31921802, 2019). "CDK2 is differentially expressed during colorectal oncogenesis and cancer progression." (PMID 31736743, 2019). "CDK2 overexpression may facilitate lymph node metastasis of early cancer, and decreased CDK2 correlates with large tumor size, venous invasion, deep infiltration, hepatic metastasis, advanced stage, and poor prognosis." (PMID 31736743, 2019). "The role of CDK2 remains controversial in several cancer types." (PMID 31921802, 2019). "Finally, we suggest that the compound (PubChem ID 101874157) would be a promising scaffold to be further exploited as a potential inhibitor of CDK2 for therapeutic management of cancer after required validation." (PMID 31847444, 2019). "In mouse cancer cells, circ-Foxo3 represses cell cycle progression by the interaction with cyclin-dependent kinase inhibitor 1 (p21) and cyclin-dependent kinase 2 (CDK2), thereby blocking the roles of p21 and CDK2 in cell cycle regulation." (PMID 31519189, 2019). "The inhibition of the PI3K signalling pathway increased sensibility of the cancer cells to CDK4/6 inhibitors palbociclib through a mechanism that could be partially attributable to the suppression of post-mitotic CDK2 activity." (PMID 30959874, 2019). "Our strategy of structure-based virtual screening of the PubChem database may open new avenues in the identification of safe and effective inhibitors of CDK2 for the development of therapeutic molecules for cancer treatment." (PMID 31847444, 2019). "It plays a key role in cell cycle progression which could accelerate the transition from G1 to S phase, and the dysregulation of CDK2 is closely related to many cancers." (PMID 31949474, 2019). "Targeting CDK2 has thus far been the only targeting approach for CCNE1 amplified cancer." (PMID 31313989, 2019). "Therefore, CDK2 and its cyclin binding partners are possible therapeutic targets for future cancer treatments." (PMID 31921802, 2019).
cancer (continued). "The CDK2 and cyclin A complex plays a vital role in the G1 phase arrest of cancer cells." (PMID 31275410, 2019). "BMS-387032 (SNS-032), a CDK2-specific inhibitor, has been identified by high-throughput screening and demonstrated to have broad spectrum anti-proliferative activity against a panel of cancer cell lines." (PMID 30135856, 2018). "Furthermore, we challenged the identified Hit against CDK2 target whose inhibition can abrupt the progression of the cancer cells." (PMID 29514608, 2018). "CDK2 is a member of the cyclin-dependent kinases family that is involved in cell replication and tumor growth, and is known to be a promising therapeutic target for cancer therapy." (PMID 30190791, 2018). "Cyclin-dependent kinase 2 (CDK2) is a potential target for treating cancer." (PMID 30423939, 2018). "In addition, cyclin-dependent kinase 2 (CDK2) has emerged as a biomarker of various cancers, making it another attractive drug target." (PMID 29184849, 2017). "Finally, CREBBP (DC = 190, BC = 512,840.8) and CDK2 (DC = 170, BC = 409,517.7) were recorded as the most potential hub genes in Cancer versus CIN group, whereas HDAC1 was a relatively low connected gene in this group (DC = 18, BC = 30,041.4)." (PMID 29312619, 2017). "Similarly, some cancer cells are known to proliferate despite CDK2 inhibition, suggesting that perhaps correlation between p21 and p27 with the cell proliferation is context dependent." (PMID 28225793, 2017). "A novel prediction of the model is that PI3K + CDK4/6 inhibition is a very effective combination treatment because of its ability to both induce cancer cell death and cell cycle arrest by suppressing two parallel proliferation regulator complexes (cyclin E and CDK2, and cyclin D and CDK4/6)." (PMID 29623959, 2017). "Based on present studies, we speculate that CIZ1 might cooperate with cyclin E, cyclin A, p21Cip1/Waf1, CDC6, or CDK2 in cancer genesis or growth, and further studies are needed to confirm this viewpoint." (PMID 26861296, 2016). "In this study, we show that RY-2f induces G2/M cell cycle arrest with down-regulation of cyclin A and CDK2, and up-regulation of p21, indicating that cancer cells may exit from G2 phase and enter M phase in response to RY-2f treatment." (PMID 26325371, 2015). "Both CDK1 and CDK2 are potential cancer targets for which selective compounds are required." (PMID 25864384, 2015). "Variolin B is in preclinical evaluation for cancer therapeutics, yet meriolins display greater specificity for CDKs than variolin B, especially CDK2 and CDK9 as well as better antiproliferative and proapoptotic features than parental counterparts in human cancer cell lines." (PMID 25625291, 2015). "As many tumors depend on Mcl-1 for chemoresistance, we investigated whether targeting cyclin E/Cdk2 could sensitize cancer cells to BH3 mimetics." (PMID 26219338, 2015). "Transfection of malignant T cells with recombinant miR-22 inhibits the expression of validated miR-22 targets including NCoA1, a transcriptional co-activator in others cancers, as well as HDAC6, MAX, MYCBP, PTEN, and CDK2, which have all been implicated in CTCL pathogenesis." (PMID 26244872, 2015). "Elevated Cdk1, Cdk2 and Cdk4 mRNA levels were detected in proliferating malignant tumors." (PMID 25900242, 2015). "Likewise, targeting the functions of CDK2 in DNA replication and S phase progression, provides a window of intervention for cancer therapeutics." (PMID 25625291, 2015).
cancer (continued). "Our results suggest that miR-302a acts as a tumor suppressor and suppresses the cancer-stemness signature in cancer cells by suppressing target genes such as CDK2 and BMI-1, although it has an important role in maintaining stemness in pluripotent cells such as ES cells and iPS cells." (PMID 24861464, 2014). "The results suggested cyclin EL highly interacts with CDK2 in Ad-infected cancer cells." (PMID 23437375, 2013). "Further, our study validated the approach of utilizing a plasmid DNA (encoding for a specific shRNA) to silence a target gene (i.e. Cdk2), disrupt the cell cycle and negatively regulate the proliferation of cancer cells (MCF-7), ultimately, leading to cell death." (PMID 23285007, 2012). "Inhibitors of Cdk2 are developed and applied in cancer therapy." (PMID 22583398, 2012). "CDK2 expression or activity has been used as a marker for the prognosis of breast, ovarian, and oral cancers." (PMID 22333595, 2012). "Recent research demonstrated that Cdk2 has an unanticipated role in suppressing Myc-induced senescence, suggesting that inhibition of Cdk2 may have therapeutic efficacy in the treatment of cancer." (PMID 22203883, 2012). "The numerous anti-proliferative effects of IFN-γ in many cancers may in part be explained by a G1 arrest involving down-regulation of G1/S cyclins (cyclins A and E) and CDK2/4." (PMID 23245396, 2012). "Studies in breast cancer have highlighted CDK2 as an essential regulator of estrogen-mediated G1/S transition; however, recent studies in non-breast cancer cell lines and in knockout mice have questioned the role of CDK2 in cancer cell proliferation." (PMID 20010939, 2010). "Our analysis reveals interesting features of cdk2 biochemistry but does not suggest that this mutation is likely to be causal for cancer." (PMID 20399812, 2010). "We hypothesized that cyclin-dependent kinase (CDK) 1 activity and CDK2 activity in cancer cells, which reflect the activation state of the spindle assembly checkpoint and the growth state, respectively, predict sensitivity to paclitaxel." (PMID 19239702, 2009). "Of these, cyclin dependent kinase 2 has a clear role in cancer cell proliferation." (PMID 18664274, 2008). "Furthermore, immunohistochemical studies showed that cdk2/cdc2 was expressed exclusively in the cancer cells positive for pRB." (PMID 7779716, 1995). "Similarly, combining ERα and CDK2 inhibition could block hormone-driven cancer growth while preventing cell cycle progression." (PMID 39861131, 2025). "Notably, others have characterized an induced dependence on POLE in CCNE/CDK2 activated cancers, thus indicating that CIC::DUX4 may operate through a similar molecular pathway." (PMID 40760094, 2025). "Hence, targeting CDK2 is considered a promising approach for controlling the progression of cancer." (PMID 39272187, 2024). "Furthermore, CDK1 and CDK2, critical regulators of the cell cycle, play a prominent role in cancer." (PMID 39457550, 2024). "Thus, CDK2 inhibition preferentially disorders centrosome stoichiometry in cancer cells." (PMID 38031910, 2023). "Thus, controlling the overexpression of CDK2 could lead to a reversed malignancy phenotype in cancer cells." (PMID 37570839, 2023). "To probe whether experimental distance restraints can act as anchors to drive predictions towards different energy minima in multistate proteins, we simulate a proof-of-concept experiment on the human cyclin-dependent protein kinase Cdk2, a drug target in cancer therapy." (PMID 36941363, 2023).